CRP (C-reactive protein)
Diseases named in the same sentence as CRP in open-access papers (continued):
Sharing a sentence is not in itself a finding about the gene and the disease.
Arthritis (continued). "This study, based on a large nationwide cohort involving 17,000 participants from most provinces in China, demonstrates that higher serum CRP levels in arthritis patients are significantly associated with increased all-cause mortality, even after adjusting for potential confounders." (PMID 39980916, 2025). "For example, routine CRP screenings could be incorporated into workplace or community health initiatives, particularly for populations at higher risk of arthritis or chronic inflammation." (PMID 39980916, 2025). "The observed association between elevated CRP levels and increased all-cause mortality in arthritis patients may be explained by several mechanisms." (PMID 39980916, 2025). "Inflammatory markers such as C-reactive protein associated with high cholesterol levels may worsen the symptoms and severity of arthritis." (PMID 38875754, 2024). "In addition, the development of arthritis is undoubtedly an important cause of reduced quality of life in elderly or even elderly patients, and arthritis as an inflammatory condition is closely associated with CRP." (PMID 36418968, 2022). "Our aim was to test whether levels of CRP or fibrinogen mediated the association between well-being and incident arthritis." (PMID 28604559, 2017). "CASP-19 at wave 1 and CRP at wave 2 were significant predictors of arthritis risk." (PMID 28604559, 2017). "However, the association between CRP at wave 2 and arthritis risk, which was attenuated (HR = 1.001, 95% CI = 1.000 to 1.002, p = .016)." (PMID 28604559, 2017). "Results were similar to those in the original analysis; a unit increase in CASP-19 intercept was associated with a 2% (p < .001) reduction in arthritis risk via the direct pathway and 0.003% reduction in arthritis risk via the indirect pathway (via CRP intercept) (p = .004)." (PMID 28604559, 2017). "We used a structural equation modeling approach to test whether inflammatory markers (C-reactive protein [CRP] or fibrinogen) mediated the association between well-being and arthritis risk for a 10-year follow-up period." (PMID 28604559, 2017). "Of the two inflammatory markers, only CRP was associated with arthritis risk." (PMID 28604559, 2017). "This pattern of attrition could have resulted in an underestimation of the association between CRP or CRP change and arthritis risk in our study as participants who left may have had a higher risk of arthritis." (PMID 28604559, 2017). "This limitation may account for the weak association between CRP and arthritis risk as well as the insignificant association between fibrinogen and arthritis risk in our sample." (PMID 28604559, 2017). "CFA-induced arthritis in rats is associated with an increase in the plasma levels of RF and CRP." (PMID 19770265, 2011). "Importantly, patients with higher levels of PLR or CRP at initial presentation were more likely to be diagnosed with PsA, suggesting that these markers may be a diagnostic help for the presence of arthritis." (PMID 37109382, 2023). "Arthritis might represent one possible cause of CRP elevation." (PMID 36743676, 2022). "When IL‐6 levels are extremely high in the context of infections (and rarely lupus serositis or arthritis), the buffering capacity is exceeded and the hepatocytes respond by producing CRP." (PMID 41591508, 2026). "Delanzomib decreased the severity of arthritis and reduced the levels of TNFα, IL-6, and CRP in rats with CIA." (PMID 40243560, 2025). "Individuals diagnosed with arthritis in 2011 were included, with CRP levels as the primary exposure variable and mortality as the outcome of interest." (PMID 39980916, 2025). "In most SLE patients, CRP levels typically remain normal even during active disease, and only mild elevation is observed in cases of SLE-associated arthritis." (PMID 41383610, 2025). "In arthritis populations, elevated CRP has been identified as a predictor of increased mortality risk, including in osteoarthritis and gout patients." (PMID 39980916, 2025).
Arthritis (continued). "Historically, high CRP levels in SLE are considered more suggestive of infection rather than disease activity, although a moderate elevation of CRP has been associated with specific SLE manifestations, namely arthritis and serositis." (PMID 41357178, 2025). "Second, many older adults have elevated CRP levels due to other common age-related conditions, such as arthritis or cardiovascular disease." (PMID 39913250, 2025). "While tofacitinib is well known to reduce serum CRP levels in arthritis models and RA patients, data on its effect on local CRP levels is sparse." (PMID 40491918, 2025). "We found that there were significant correlations between patient age, pregnancy weeks, numbers of delivery, and levels of PRL (P<0.05), but also between levels of ESR and CRP, erythema nodosum and arthritis (P<0.05)." (PMID 41001015, 2025). "The two patients highlighted in this case presented with arthralgias, arthritis, and elevated CRP levels following COVID-19 infections." (PMID 40078238, 2025). "The study highlights the need to reconsider CRP’s role in arthritis, emphasizing its potential protective role before disease onset and encouraging further research to develop CRP based therapeutic strategies." (PMID 40943152, 2025). "The present case suggested the importance of considering GABHS infection in patients with a sore throat, systemic skin rash, and arthritis with uncertain causes, even when the patient is afebrile and the WBC count and CRP level are normal." (PMID 39936085, 2025). "HLA-B*35 was present in 29.2% of patients with inflammatory low back pain, 21.6% with reduced lumbar mobility, 23.3% with radiographic sacroiliitis, 28.9% with arthritis, 24.4% with enthesitis, and 34.6% with elevated CRP/ESR levels." (PMID 40806743, 2025). "Two patients who developed inflammatory arthritis following COVID-19 infection are presented, characterized by arthralgias, arthritis, and elevated markers of inflammation (C-reactive protein)." (PMID 40078238, 2025). "By predicting the interactions of CRP and OST with PADI4, a key arthritis-associated gene, PICKLE helps elucidate how these proteins contribute to inflammatory pathways." (PMID 40266392, 2025). "Only one patient responded poorly to tofacitinib treatment, which manifested as a persistent elevation in CRP and ongoing symptoms of arthritis." (PMID 40909428, 2025). "The chance of developing symptoms of arthritis is increased by CRP, which is elevated by all infections." (PMID 38699124, 2024). "For example, high CRP levels are common in autoinflammatory diseases, such as vasculitis and arthritis, even when white blood cell counts remain normal or only moderately elevated." (PMID 39995828, 2024). "Recent studies have shown a strong correlation between the synovial expression of IL-34 and factors such as rheumatoid factors, erythrocyte sedimentation rate, CRP, and the progression of arthritis on radiographic imaging." (PMID 38481325, 2024). "AOSD can be considered in the differential diagnosis with VEXAS due to the similarities in several clinical features (e.g., recurrent fever, arthralgia, arthritis, skin rash, and pleuritis) and laboratory markers of inflammation (like high CRP and ferritin)." (PMID 39251478, 2024). "CRP levels above 3 mg/l were found in 66.0% of arthritis patients, compared to 13.6% in control subjects (p < 0.001)." (PMID 39167172, 2024). "Previously published data suggest a protective function of CRP in arthritis; however, the mechanism of action of CRP remains undefined." (PMID 38650931, 2024). "CRP reduced the incidence of arthritis, that is, reduced the number of mice with developing arthritis." (PMID 38650931, 2024). "By employing CRP-deficient mice and mice expressing human CRP transgene in CIA experiments in mice, it was concluded from the data that CRP exerts an early and beneficial effects on the development of arthritis." (PMID 38650931, 2024).
Arthritis (continued). "RA is one type of inflammation that can be brought on by elevated levels of CRP in patients with arthritis as compared to controls." (PMID 38699124, 2024). "It was reported that higher CRP levels were found in patients with active serosits, arthritis, and myositis." (PMID 38302903, 2024). "Studies have shown that C-reactive protein and erythrocyte sedimentation rate are correlated with the prevalence of PD, and they are also biomarkers of arthritis." (PMID 39234184, 2024). "Our finding that CRP prevented rise in the serum level of IL-17 suggests that IL-17 is more critical than TNF-α for the initiation of the development of arthritis." (PMID 38650931, 2024). "CRP levels exceeding 3 mg/l were found in 66.0% of arthritis patients (RA 69.2%, PsA 62.5%), significantly higher than the 13.6% observed in the control subjects (p < .001)." (PMID 39692860, 2024). "The rat model of arthritis also exhibited significant inflammatory response, and peptide BG can significantly inhibit serum pro-inflammatory factor levels, including IgM-RF, CRP, IL-1β, IFN-γ, and TNF-α." (PMID 39669913, 2024). "Studies in patients with arthritis showed that W-BC helped reduce inflammatory markers such as IL-6, tumor necrosis factor, and serum CRP." (PMID 39576692, 2024). "In particular, there was a significant reduction in CRP levels among arthritis patients, especially within the first three months following treatment initiation (p < .001)." (PMID 39692860, 2024). "Increased arthritis disease activity was associated with higher levels of inflammatory cytokines (IL-6, TNF and CRP) and immunoregulatory cytokine IL-10 (p<0.05)." (PMID 38507338, 2024). "All study participants had previously experienced tocilizumab treatment failure with active sJIA, with symptoms such as fever, arthritis, elevated CRP, and ESR." (PMID 38504360, 2024). "Radiographic progression was not assessed in this study, but patients in both tofacitinib groups had more decreases in swollen and tender joint count, PGA of arthritis, Psoriatic Arthritis Response criteria (PsARC), and CRP levels when compared to placebo." (PMID 38731900, 2024). "Serum C-reactive protein concentration in patients with active arthritis significantly increased compared with after acute KD treatment (2.4 vs. 0.7 mg/dL, p < 0.001)." (PMID 37336934, 2023). "These should include full blood count, kidney and liver function tests, creatine kinase (in case of suspected concomitant myositis), rheumatoid factor (in case of suspected concomitant arthritis) and C-reactive protein (CRP)." (PMID 36860340, 2023). "In comparison to the normal group, arthritis induction resulted in a significant (p ≤ 0.05) elevation in RF, CRP, and PGE2 levels in the sera of the model group." (PMID 37893036, 2023). "Vielversprechende alternative Biomarker sind Calprotectin und Osteopontin, die bereits bei der rheumatoiden Arthritis die Erkrankungsaktivität unabhängig vom CRP widerspiegeln konnten." (PMID 37184675, 2023). "The serum CRP concentration during the active phase of arthritis was significantly higher than after treatment for KD during the acute phase (p < 0.001)." (PMID 37336934, 2023). "The main clinical features are spondylitis, arthritis, uveitis, dactylitis, and an elevated level of C-reactive protein." (PMID 37238999, 2023). "The administration of PeaNoc XL as an adjunct to standard therapy resulted in a significant reduction in levels of TNF-α (P<0.01), IL-1β (P<0.001), IL-6 (P<0.01), and CRP (P<0.01) in arthritis patients experiencing joint pain and inflammation." (PMID 37767025, 2023). "Significantly higher CRP, sedimentation, and significantly lower hemoglobin were detected in those with arthritis (respectively P < .001 and P = .007)." (PMID 37403914, 2023). "The systemic biomarkers of arthritis like RF, CRP, ESR, WBCs, and platelets were notably altered in arthritic rats that were restored by treatment." (PMID 37113751, 2023).
Arthritis (continued). "Although her arthritis partially improved with the addition of golimumab, she continued to have arthritis in her hands, and her CRP remained elevated." (PMID 35363175, 2022). "Another study showed a protective effect of CRP at the beginning of arthritis using rabbit CRP-transgenic mice." (PMID 35047645, 2022). "Accordingly, we diagnosed her as having post-COVID-19 vaccine J01 syndrome (arthritis, inflammatory myalgia, Gottran' patch, positive J01, strongly positive anti-Ro antibody, raised CRP and platelet, with excellent response to steroid)." (PMID 36199642, 2022). "In summary, the joints of CRP + SSc patients exhibited arthritis more often than the joints of CRP− SSc patients." (PMID 36743676, 2022). "Three proteins (complement component 9, C-reactive protein, and α-1, β-glycoprotein) were found to be significantly differentially expressed and are known as inflammatory mediators playing critical roles in arthritis pathogenesis." (PMID 35433699, 2022). "For GLM patients with erythema nodosa and arthritis, C-reactive protein abnormally increases, and ANA and rheumatoid are normal." (PMID 35473758, 2022). "The top 10 variables ranked by importance were disease duration, L%, N%, NLR, sex, CRP, shawl sign, arthritis/arthralgia, V-neck sign, and anti-PM-Scl75 antibodies." (PMID 35237262, 2022). "Diseases with an established serological biomarker for disease monitoring appear favorable for self-sampling, such as CRP for arthritis patients or anti-dsDNA antibodies for SLE patients." (PMID 36461025, 2022). "Rash, recurrent fever, arthritis/arthralgia, uveitis, sensorineural deafness, symptoms of central neural systems (CNS), and increased inflammatory markers (including CRP, ESR, except Ferritin) were the common findings in Chinese patients." (PMID 35668534, 2022). "Efficacy was evaluated by analyzing fever, skin rash, arthritis, pericarditis, hepatosplenomegaly, CRP, ESR, and serum ferritin." (PMID 34868356, 2021). "IL-6 inhibition ameliorated joint swelling, accompanied by remarkably reduced plasma CRP levels when HZ-0408b was administrated after the onset of arthritis in the monkey CIA model." (PMID 35126375, 2021). "The effects of TCZ on our RA patient cohort concurred with the known effects of TCZ, showing clinical improvement in arthritis, and causing reductions in DAS28 scores and high sensitivity CRP levels." (PMID 34975837, 2021). "Five RA-individuals developed arthritis within 39.67 [23.77–66.04] months of follow-up, with CRP levels of 3.15 [1.14–22.07] mg/l and a DAS28-CRP score of 3.41 [2.53–4.50] at the time of arthritis manifestation." (PMID 33633196, 2021). "Most importantly, we proved that HZ-0408b treatment significantly ameliorated joint swelling after the onset of arthritis and dramatically reduced plasma C-reactive protein (CRP) levels in a monkey collagen-induced arthritis (CIA) model." (PMID 35126375, 2021). "RA is an inflammatory disease, and the inflammatory markers are highly expressed in synovial fluid and serum of patients with arthritis, such as C-reactive protein (CRP: an acute-phase protein), interleukin-6 (IL-6), and tumor necrosis factor (TNF-α)." (PMID 34136020, 2021). "Visual inspection and biochemical examinations including TNF-α, interleukin 6, and C-reactive protein were performed to assess arthritis severity during the treatment." (PMID 34880764, 2021). "Two individuals developed arthritis within 16.61 [8.91–24.30] months of follow-up, with CRP levels of 31.54 [14.50–48.57] mg/l and a DAS28-CRP score of 4.79 [4.71–4.87] at the time of arthritis manifestation." (PMID 33633196, 2021). "Persisting activity at last visit consisted mainly of arthralgias/arthritis, and elevated CRP, less frequently of low-grade fever, lymphadenopathy, serositis, rash, increased white cell count, anemia, elevated ferritin, ESR, and platelet count." (PMID 34868356, 2021).
Arthritis (continued). "The low correlation of these indices with TMJ parameters inevitably occurs, because high levels of ESR and CRP can occur secondary to any arthritis in the body." (PMID 32161274, 2020). "Her laboratory examinations always showed increased ESR and CRP and, despite treatments, her arthritis was evolving with significant limitations." (PMID 33092242, 2020). "Next we overview evidence that we and others have generated using animal models of arthritis, neointimal hyperplasia, and acute kidney injury that baseline CRP exerts important biological effects." (PMID 33633738, 2020). "The average disease activity score (based on clinical arthritis parameters and CRP, and expressed as DAS28CRP) was 5.1 (high disease activity) in the DRA group, and 4.5 (moderate disease activity) in the NDRA group." (PMID 30718650, 2019). "The observation of chronic lesions in young children and adults with hepatosplenomegaly, arthralgia/arthritis, high CRP, and microcytic anemia is suggestive of Hz/Hc." (PMID 31789267, 2019). "Proportions of patients achieving Juvenile Arthritis Disease Activity Score in 27 joints using C-reactive protein (JADAS27-CRP) remission (score < 1) and minimal disease activity (MDA; score < 3.8), were among exploratory endpoints." (PMID 31039807, 2019). "The tendon thickness in the group of PsA patients was found to be significantly affected by duration of psoriasis and of arthritis, the nail bed thickness, CRP concentration and the swollen joints count." (PMID 30842536, 2019). "Higher concentrations of CRP in the plasma is reported to indicate expanded joint changes in arthritis." (PMID 31727971, 2019). "The second patient was 15 years old, with arthritis in 10 joints, and with a CRP of 7.4 mg/dL at diagnosis." (PMID 29304824, 2018). "The CRP levels were stable while progressing from CSA to clinical arthritis (mean 9.8 and 9.1 mg/L respectively, p = 0.83) and decreased during the first year of treatment (mean 5.5 mg/L; p = 0.056)." (PMID 29724244, 2018). "Ermittelt wurden der Arthritis-Score sowie die Serumspiegel von Tumornekrosefaktor-alpha (TNF-α), IL-6 und C‐reaktivem Protein (CRP) anhand der Messung mittels ELISA-Test („enzyme-linked immunosorbent assay“)." (PMID 27900440, 2018). "An additional intriguing finding is that ESR and CRP values correlate well not only with severity of arthritis and inflammatory marker levels, but also with Hb levels in both RRP and non-RRP groups." (PMID 29408886, 2018). "Similar patterns to those observed in ESR were observed in the relationship between CRP levels and arthritis scores and inflammatory marker levels, including WBC and Hb in both RRP and non-RRP groups." (PMID 29408886, 2018). "On univariate analysis, ESR, CRP, and type IIB vessel involvement were significantly associated with arthritis (p = 0.007, p = 0.027, and p = 0.004, respectively)." (PMID 29996949, 2018). "Arthritis score, tumor necrosis factor (TNF)-α, interleukin (IL)-6, and C reactive protein (CRP) levels in the serum were measured by enzyme-linked immunosorbent assay (ELISA)." (PMID 27900440, 2018). "The CASP-19 is designed to assess hedonic and eudemonic well-being; higher CASP-19 scores have previously been associated with lower levels of CRP and fibrinogen in women, and an abridged (12-item) version of the CASP has been found to predict arthritis risk." (PMID 28604559, 2017). "Both drugs significantly suppressed clinical symptoms of arthritis, C-reactive protein (CRP) and IL-6 inflammatory biomarkers, and anti-collagen type II serum antibody responses (both IgM and IgG)." (PMID 31548534, 2017). "CFA induced arthritis in rats increased the CRP and RF level as evidenced in the inflammatory process as shown by the results of the arthritis control group in this study." (PMID 28202019, 2017). "In this study, the first pilot cohort of patients with RA had significantly increased circulating CTHRC1, and high CTHRC1 correlated with increased CRP and with aggravated arthritis." (PMID 27430622, 2016).